NEAT1 (nuclear paraspeckle assembly transcript 1)
Diseases named in the same sentence as NEAT1 in open-access papers (continued):
Sharing a sentence is not in itself a finding about the gene and the disease.
COVID-19 (continued). "In the moderate COVID-19 group, NEAT1 was negatively correlated with oxygen but positively with age, TUG1 expression, CCL2, TNF-α, and IL-6 expression." (PMID 35982898, 2022). "NEAT1 was overexpressed in nine cell types identified from severe COVID-19 patient BAL samples, including in M1 and M2-type macrophages, monocytes, CD4+ T cells, and CD8+ memory T cells." (PMID 34564316, 2021). "Further research into the roles of MALAT1 and NEAT1 in the context of COVID-19 will be valuable in further understanding the mechanism behind disease progression in the perusal of potential biomarkers and therapeutic intervention." (PMID 32646047, 2020). "Another study suggested that NEAT1 could also be critical for regulating the Th1/Th2 balance in the patients infected with SARS-CoV-2 (COVID-19)." (PMID 40362651, 2025). "And similar to lncRNAs, ANRIL, THRIL, and NEAT1 are significantly upregulated in COVID-19 patients, suggesting their measurement could predict severity and improve clinical outcomes." (PMID 40144645, 2025). "The upregulation observed of GAS5, NORAD, BISPR, and NEAT1 in dRNA-seq of infected Calu-3 cells (between 1.03- and 1.11-fold) is consistent with upregulation of these lncRNAs in COVID-19 patients (1.05- and 1.17-fold) in the two datasets (GSE171110 and GSE157103)." (PMID 41267684, 2025). "Recent studies suggested that the upregulation of NEAT1 and MALAT1 may be associated with inflammation and consequent tissue damage seen in severe COVID-19." (PMID 38397917, 2024). "The strengths of our study include that it is the first time to detect decreased NEAT-1 in the serum of COVID-19 patients and the first study to measure serum miR374b-5p in COVID-19 patients and to correlate its level with NEAT-1, IL6, and other laboratory findings." (PMID 39729489, 2024). "Fold change of NEAT1, miR374b-5p, and IL-6 levels in COVID-19 and healthy controls." (PMID 39729489, 2024). "Interestingly, NEAT1 was increased in saliva samples of patients with COVID-19, thus, being a possible biomarker of the disease." (PMID 38203577, 2023). "NEAT1 was overexpressed in both mild and severe forms of COVID-19." (PMID 38203577, 2023). "In addition, multiple studies have shown that MALAT1 and NEAT1 are expressed differently in patients with COVID-19." (PMID 36852336, 2023). "Moreover, NEAT1 expression was higher in the moderate COVID-19 group than in the controls (P<0.001)." (PMID 35982898, 2022). "Multivariate COX regression analysis revealed that NEAT1 is an independent predictor for survival among COVID-19 patients with an odds ratio of 7.48 and 95% CI (1.03 - 36.08) (P=0.02) while (male sex, smokers, CCL2, TNF-α, and IL-6) were cofactors affecting overall survival." (PMID 35982898, 2022). "These highly inflammatory and damaging effects of NEAT1 illustrate how overexpression in severe patients might lead to the inflammatory tissue damage seen in severe COVID-19." (PMID 35007307, 2022). "Therefore, the current study aimed to investigate lncRNAs, particularly NEAT1 and TUG1, and their association with IL-6, CCL2, and TNF-α in COVID-19 patients with moderate and severe disease." (PMID 35982898, 2022). "Lastly, our observation that CTSL, a protein crucial for COVID-19 viral entry is upregulated across multiple cell types in severe patients provides a potential initial mechanism for the induction of the NEAT1 and MALAT1 mediated inflammatory state through increased efficiency of viral entry." (PMID 35007307, 2022). "The lncRNAs NEAT1 and MALAT1 are potential components of immune dysregulation in COVID-19 that may provide targets for severity related diagnostic measures or therapy." (PMID 33821282, 2021). "By classifying lung transcriptomic data from apparently healthy GTEx donors to inflammation-prone or resilient, we found the expression of lncRNAs DANCR and NEAT1 to predict the inflammatory profile exhibited by involved tissues, and reflect on adverse body and brain consequences of COVID-19." (PMID 33163005, 2020).
COVID-19 (continued). "Thus, DANCR and NEAT1 both appear to act as kernels to a network of genes involved in inflammation and diverse infections, at least in the context of COVID-19." (PMID 33163005, 2020). "Consequently, NEAT1 expression is significantly upregulated in peripheral blood mononuclear cells (PBMCs) and serums of patients infected with various viruses, including COVID-19 and human immunodeficiency virus 1 (HIV-1)." (PMID 40362651, 2025). "Thus, NEAT1 and MALAT1 are potential components of immune dysregulation in COVID-19 that may provide targets for severity related diagnostic measures or therapy." (PMID 35007307, 2022). "Our study aimed to measure NEAT-1, miR-374b-5p, and IL6 in the serum of COVID-19 patients, demonstrating the correlation between target genes to explore the possible relationship between them." (PMID 39729489, 2024). "Our study aimed to measure NEAT-1, miR-374b-5p, and IL6 in the serum of COVID-19 patients, demonstrating a correlation between target genes to explore the possible relationship between them." (PMID 39729489, 2024). "NEAT1 has been shown to be differentially expressed in bronchoalveolar lavage (BAL) cells in severe and mild COVID-19 patients." (PMID 36950105, 2023). "The lncRNAs NEAT1, MALAT1, and Tug1 are lncRNA-related therapeutic targets for the treatment of COVID-19 patients." (PMID 36204652, 2022). "According to previous studies, lncRNA MALAT1, lncRNA NEAT1, and lncRNA TUG1 were upregulated in COVID-19." (PMID 36204652, 2022). "MALAT1 and NEAT1, whose upregulation in SARS-CoV-2 infected cell lines and in BALF from COVID-19 patients was discussed earlier, also stand out in the comparative analysis of severe vs. non-severe cases." (PMID 36052163, 2022). "Four lncRNAs, MALAT1, NEAT1, TUG1 and GAS5 are predicted as potential therapeutic targets in COVID-19." (PMID 36204652, 2022). "Very recently it has been shown that that NEAT1 and MALAT1 are highly expressed in saliva and nasopharyngeal swab samples of COVID-19 patients confirming the result in the present study." (PMID 34940755, 2021). "MALAT1, NEAT1, and SNHG25 long noncoding RNAs (lncRNAs) were downregulated in mild and severe COVID-19 BAL cells." (PMID 33138195, 2020). "Gene signatures from three lncRNA gene markers (MALAT1, NEAT1, and SNHG25) were found to be downregulated in mild and severe cases of COVID-19, compared to normal controls." (PMID 33138195, 2020). "Thus, the non-coding regulators igniting and propagating COVID-19 may provide potential mechanistic explanations to the hazards incurred by at-risk populations, and our findings bring ncRNAs at large, and DANCR and NEAT1 in particular, to the realm of COVID-19 and its aftermath." (PMID 33163005, 2020). "Further downregulation of MALAT1 and NEAT1 was observed in mild-COVID-19 BAL cells, while SNHG25 was markedly downregulated in both mild- and severe-COVID-19 BAL cells." (PMID 33138195, 2020). "However, the characteristics and mechanisms of action of NEAT1 and MALAT1 in COVID-19 are still unclear." (PMID 36852336, 2023). "Since NKG7 is important for cytotoxic degranulation and downstream inflammation and NEAT1 is an activator of the NLRP3 inflammasome, their downregulation may indicate an induced shift away from an inflammatory state in COVID-19 patients." (PMID 36992700, 2023). "This striking overexpression of NEAT1 and TUG1 in severe and moderate COVID-19 patients may explain the prominent role of lncRNAs in COVID-19 and may augment their use as targets for control and downregulation in the management of COVID-19 infection." (PMID 35982898, 2022). "Thus, the high level of MALAT1, NEAT1 and EGOT observed in COVID-19 patients potentially work together and are correlated to the delayed IFN-I response." (PMID 36052163, 2022). "LncRNAs can monitor cholinergic signaling in response to COVID-19; lncRNA DANCR and lncRNA NEAT1 affect nerve tissues through cholinergic mediators, and their upregulation may change the inflammatory state of neurons." (PMID 36204652, 2022).
COVID-19 (continued). "Furthermore, both NEAT1 and MALAT1 have been recently connected to COVID-19 related inflammation, emphasizing a need for additional study of these lncRNAs." (PMID 35007307, 2022). "Finally, we predict the possible therapeutic targets of four lncRNAs, MALAT1, NEAT1, TUG1, and GAS5, in COVID-19." (PMID 36204652, 2022). "NEAT1 and TUG1 had significant correlations with the measured cytokines, and based on the multivariate regression analysis, NEAT1 is the independent predictor for survival in COVID-19 patients (P=0.02)." (PMID 35982898, 2022). "NEAT1 and MALAT1 are differential regulators of inflammation in severe COVID-19." (PMID 33821282, 2021). "The ubiquity of NEAT1, its specific localization to BAL cells, and pro-inflammatory functions suggests that it may be a key mediator of the inflammation seen in severe COVID-19." (PMID 33821282, 2021). "Additionally, MALAT1, NEAT1, and SNGH25 were downregulated in patients with mild and severe COVID-19." (PMID 33138195, 2020). "Furthermore, we identified significant positive correlations between NEAT1 and CCL2, and IL-6, which may explain its pathological role in COVID-19 by targeting CCL2 and IL-6 and increasing their production, specifically in the severe form of the disease." (PMID 35982898, 2022). "Furthermore, the effects of MALAT1, NEAT1 and XIST are correlated with COVID-19 severity." (PMID 36052163, 2022). "The ubiquity of NEAT1, its specific localization to BAL cells, and its pro-inflammatory functions suggests that it may be a key mediator of the inflammation seen in severe COVID-19." (PMID 35007307, 2022). "Taken together, our findings may assist future management of COVID-19 patients, as they may exhibit diverse expression profiles of molecular regulators such as DANCR and NEAT1, in conjunction with previously depicted inflammatory mediators such as IL-1, IL-6, TNF, and more." (PMID 33163005, 2020). "Interestingly, the NEAT1 in the BAL cell types was generally under-expressed in mild samples compared to healthy samples, suggesting that a mechanism of NEAT downregulation may also protect mildly affected COVID-19 patients." (PMID 34564316, 2021).
lymph node metastasis (25 papers, 2015 to 2025). "Our results indicated that the Neat1 SNP rs3825071, with the CT+TT heterozygote, significantly lowered the risk of lymph node metastasis." (PMID 40027195, 2025). "In conclusion, our examination demonstrates associations between Neat1 gene variants and clinical stage as well as lymph node metastasis in tongue cancer patients, particularly among Taiwanese males carrying the Neat1 rs3825071 polymorphism." (PMID 40027195, 2025). "Promisingly, NEAT1 holds diagnostic potential, correlating with advanced disease stages, lymph node metastasis, and poor prognoses." (PMID 38343745, 2024). "A recent study further indicated that higher NEAT1 expression has positively association with lymph node metastasis and tumor node metastasis staging in BC patients, which was in line with our results." (PMID 33820555, 2021). "Moreover, they also provided the evidence that the high level of NEAT1 is associated with clinical stage, histological type, lymph node metastasis, and distant metastasis of GC." (PMID 33292252, 2020). "NEAT1 levels were found to be significantly higher in endometrioid EC tissue than in normal endometrial tissue, and higher levels of NEAT1 were positively associated with advanced tumor stage and lymph node metastasis." (PMID 31287002, 2019). "Moreover, to assess the clinical significance of NEAT1, we evaluated the association between its expression and clinic-pathological parameters (including lymph node metastasis, maximum diameter, and stage and so on)." (PMID 27351135, 2016). "Higher level expression of NEAT1 also indicated the severe lymph node metastasis stage (p < 0.01) as well as poor disease-specific survival (p=0.036) and overall survival (p=0.018) in cohort GSE17536." (PMID 36262350, 2022). "NEAT1 expression in serum EVs was high and related to lymph node metastasis, progesterone receptor, estrogen receptor and Ki-67 in BC patients." (PMID 33820555, 2021). "Higher expression of NEAT1 was associated with TNM stage, lymph node metastasis, and clinical stage." (PMID 33330110, 2020). "The expression of NEAT1 in clear cell renal cell carcinoma (ccRCC) was also found to be enhanced in tumor tissues, which positively correlated with tumor size, lymph node metastasis, and also predicted short 5-year survival rate of patients with ccRCC." (PMID 29654165, 2018). "Elevated NEAT1 expression significantly predicted lymph node metastasis (HR: 2.10, 95% CI: 1.32–3.33, P = 0.002) and distant metastasis (HR: 2.80, 95% CI: 1.60–4.91, P = 0.0003) respectively." (PMID 29026116, 2017). "In particular, patients with grade T3 to T4, lymph node metastasis, poor differentiation, or advanced clinical stages expressed higher levels of NEAT1." (PMID 26822763, 2016). "In this study, we identified that NEAT1 was up‐regulated in OC patients and cell lines, and its expression was associated with the FIGO stage and lymph node metastasis." (PMID 27075229, 2016). "Tumors with grade T3 to T4, lymph node metastasis, or advanced clinical stages expressed higher levels of NEAT1." (PMID 26822763, 2016). "Higher levels of NEAT1 may be positively correlated with advanced tumor stage and lymph node metastasis." (PMID 39188680, 2024). "Higher expression of NEAT1 was associated with TNM stage and lymph node metastasis." (PMID 33330110, 2020). "Higher expression of NEAT1 was associated with TNM stage, tumor size, and lymph node metastasis." (PMID 33330110, 2020). "Higher expression of NEAT1 was associated with a TNM stage and lymph node metastasis." (PMID 32296457, 2020). "Furthermore, elevated NEAT1 expression significantly predicted lymph node metastasis (HR: 2.10, 95%CI: 1.32–3.33, P = 0.002) and distant metastasis (HR: 2.80, 95%CI: 1.60–4.91, P = 0.0003) respectively." (PMID 29026116, 2017). "It was shown that the expression of NEAT1 is associated with lymph node metastasis rather than TNM stage (*p<0.05, **p<0.01)." (PMID 29050268, 2017).
lymph node metastasis (continued). "A number of studies have shown that NEAT1 affects various clinicopathological features such as TMN stage, tumor size, lymph node metastasis, and distant metastasis in cancer patients." (PMID 38970092, 2024). "lncRNA NEAT1 was related to TNM staging, lymph node metastasis, distant metastasis, poor prognosis, and other clinicopathological features." (PMID 36185217, 2022). "The relationship between lncRNA NEAT1 expression and lymph node metastasis was reported in 5 papers with a total of 144 cases with lymph node metastasis and 187 cases without lymph node metastasis." (PMID 39139172, 2024). "To validate our clinical analysis, we used The Cancer Genome Atlas (TCGA) database to confirm whether NEAT1 is correlated with NSCLC, stage, lymph node metastasis, and smoking." (PMID 32296457, 2020). "There was a marked difference of NEAT1 expression between GAC with or without lymph node metastasis (LNM) (P = 0.004)." (PMID 26911892, 2016). "Next, we compared the NEAT1 lncRNA expression between tumor groups with (n = 85) or without lymph node metastasis (n = 46)." (PMID 26911892, 2016). "GACs with lymph node metastasis (LNM) expressed higher levels of NEAT1 lncRNA compared with those without LNM (P = 0.004)." (PMID 26911892, 2016). "Interestingly, we found that the higher NEAT1 was positively correlated with the FIGO stage of tumor and the occurrence of lymph node metastasis, but not with other clinicopathological variables." (PMID 27075229, 2016).
Huntington disease (24 papers, 2013 to 2025). Huntington disease (HD) is a rare neurodegenerative disorder of the central nervous system characterized by unwanted choreatic movements, behavioral and psychiatric disturbances and dementia. "This larger validation cohort revealed consistent elevation in both PD and PD models of NEAT1, which has been implicated in Huntington's disease (HD) and in murine PD models as well as LINC‐PINT, but RMST’s qPCR levels showed no disease‐related changes." (PMID 32080970, 2020). "Altered NEAT1 levels were evident in Huntington’s disease cells and postmortem brain tissues, and huntingtin knockdown decreased NEAT1 levels." (PMID 39028820, 2024). "And thus, upregulation of NEAT1 expression was reported by reanalysis of microarray data from human Huntington’s disease brains." (PMID 35796900, 2022). "The lncRNA Neat1 was found to be significantly upregulated in the caudate nucleus in Huntington’s disease and plays an important role in innate immunity." (PMID 34410604, 2021). "For example, nuclear paraspeckle assembly transcript 1 (NEAT1) was obviously increased in the brain region of Huntington’s disease patients." (PMID 33726823, 2021). "Growing evidence highlights a deregulation of NEAT1 expression also in neurodegenerative diseases, including Huntington’s disease (HD), amyotrophic lateral sclerosis (ALS) and Parkinson’s disease (PD)." (PMID 32630183, 2020). "In Huntington’s disease, the nuclear paraspeckle assembly transcript 1 (lncRNA NEAT1) has been shown to promote neuroprotection by adding neurons." (PMID 33245101, 2020). "Microarray analyses as well as quantitative PCR of post-mortem brains of Huntington’s disease patients and R6/2 mouse brains—a model for HD—show an upregulation of NEAT1 expression." (PMID 30717168, 2019). "Nuclear paraspeckle assembly transcript 1 (NEAT1) is known to be involved in neurological disorders including amyotrophic lateral sclerosis and Huntington’s disease." (PMID 29653596, 2018). "NEAT1 also participates in neurodegenerative diseases such as Huntington's disease and seems to potentially contribute to the elevated production of a number of cytokines and chemokines in patients with systemic lupus erythematosus (SLE)." (PMID 28202761, 2017). "For example, MALAT1 and NEAT1 are bound by the Huntington’s disease induced genes, TDP-43 and FUS, which make them important actors in synapse formation." (PMID 29189723, 2017). "Previous studies have suggested that NEAT1 lncRNA has an important structural role in the nuclear paraspeckles and it plays important roles in Huntington's disease by disrupting neuron differentiation, which coincides with our predicted functions." (PMID 25815337, 2015). "NEAT1 is upregulated in Huntington’s disease and may be protective of polyglutamine repeat toxicity." (PMID 32471155, 2020). "Some lncRNAs, including myocardial infarction associated transcript (MIAT), metastasis-associated lung adenocarcinoma transcript 1 (MALAT1), and nuclear enriched abundant transcript 1 (NEAT1), influence neurodegenerative diseases such as Huntington’s disease and AD." (PMID 30469430, 2018). "Importantly, Sunwoo and colleagues showed that NEAT1 is overexpressed in Huntington’s disease patients and plays a protective role against cell injury." (PMID 29997370, 2018). "For instances, NEAT1 was found to contribute to the pathogenesis of lupus; altered expression of NEAT1 was also found in the Huntington's disease; NEAT1 is required for mammary gland development and lactation, which suggests the diverse functional roles of NEAT1." (PMID 27926523, 2017). "NEAT1 is upregulated in the brain of patients with Huntington’s disease." (PMID 29189723, 2017). "NEAT1 is upregulated in Huntington's disease and involved in HIV replication." (PMID 26578588, 2016). "Also the up-regulation of NEAT1 is reported in Huntington’s disease." (PMID 27050411, 2016).